SDHB (succinate dehydrogenase complex iron sulfur subunit B)
Diseases named in the same sentence as SDHB in open-access papers (continued):
Sharing a sentence is not in itself a finding about the gene and the disease.
infection (10 papers, 2009 to 2023). The state of being infected such as from the introduction of a foreign agent such as serum, vaccine, antigenic substance or organism. "Sequencing of the D39 population recovered from the mice at 24 h postinfection demonstrated that the sdhB genotype frequency had increased during each of these infections, becoming fixed in 7/11 mice." (PMID 36507681, 2023). "LubX specifically seem to target SidH during infection even though other effectors of the SdhA family, SdhA and SdhB, share high sequence homology with SidH in the N-terminal 700 residues." (PMID 37923743, 2023). "The fate of the sdhB genotype over the course of the infection was thus a strong determinant of the severity of that infection." (PMID 36507681, 2023). "Interestingly, deletion of SdhA alone results in defective growth in mouse macrophages while deletion of the two paralogues SidH and SdhB does not cause any significant growth phenotype indicating that these paralogs may have different functions during infection." (PMID 37923743, 2023).
genetic disorder (7 papers, 2010 to 2024). "Genetic disorder is another factor in occurrence, and SDHB is the most common gene associated with the highest rate of metastasis." (PMID 38645508, 2024). "SDHB germ line mutation is the most common genetic disorder in PPGLs." (PMID 34181326, 2021). "Among the familial cases, MEN2 was the most common genetic disorder, affecting 23% of the sample, with a further 4 cases associated with NF1, MAX, and SDHB pathological variants." (PMID 36896586, 2023).
mitochondrial disease (4 papers, 2018 to 2022). "Although complex II deficiencies are exceedingly uncommon (almost 2–8% of mitochondrial disease cases), either homozygous or heterozygous pathogenic variants are reported in SDHA, SDHB, and SDHD genes, leading to some primary mitochondrial disease such as Leigh or Leigh-like syndrome." (PMID 35160083, 2022). "Mutations in genes encoding for either structural subunits or assembly factors have been described (SDHA, SDHB, SDHD, and SDH assembly factor 1 (SDHAF1) for mitochondrial diseases; SDHD, SDHC, SDHB, SDHA, and SDHAF2 for hereditary paragangliomas)." (PMID 30030362, 2018).
neurodegenerative disease (4 papers, 2015 to 2025). A disorder of the central nervous system characterized by gradual and progressive loss of neural tissue and neurologic function. "In contrast, in PF tissue, genes like ATP5F1A, ATP5PO, SDHB, NDUFS8, SDHA, and COX5A play roles within the neurodegenerative disease pathway, and PF tissue has a positive impact on the process related to degenerative diseases." (PMID 40136641, 2025). "An important property of the neurodegenerative diseases is the downregulated oxidative phosphorylation because of the dysfunctional brain mitochondria and the varied genes including UQCRC1, UQCR10, SDHB, ATP5B, ATP5C1, NFUFA1, and VDAC1." (PMID 29359159, 2017). "IF regulates lipid metabolism primarily via genes including FABP4, WNT10B, PCK1, PLIN1, LEPR, and ADIPOQ, providing energy for cold adaptation, whereas PF positively influences in vivo degenerative diseases mainly through genes such as ATP5F1A, ATP5PO, SDHB, NDUFS8, SDHA, and COX5A." (PMID 40136641, 2025).
CNS tumors (2 papers, 2013 to 2019). "In the present study, we investigated the loss of SDHB immunoexpression in 90 cases of CNS tumors." (PMID 30971719, 2019). "Mutations in SDHB and depression of SDH activity have been strongly implicated in neuronal aging and in development of CNS tumors." (PMID 23543038, 2013). "Furthermore, to the best of our knowledge, the loss of SDHB immunoexpression has not been explored in various types of CNS tumors." (PMID 30971719, 2019). "Among the 90 cases of CNS tumors, only 3 (3.3%) showed no immunoexpression of SDHB protein." (PMID 30971719, 2019).
gastrointestinal tumors (2 papers, 2021 to 2023). "Consistently, immunohistochemical staining in SDHA-related gastrointestinal tumors reveals normal SDHA but lowered SDHB expression." (PMID 37945749, 2023).
autosomal dominant disease (1 paper, 2017). Autosomal dominant form of disease. "While SDHB (1p36) and VHL (3p25) are associated with autosomal dominant disease, SDHD (11q23) and SDHAF2 (11q13) show a remarkable parent-of-origin effect whereby tumor formation is almost completely dependent on paternal transmission of the mutant allele." (PMID 28099933, 2017).
head or neck tumors (1 paper, 2014). "SDHB mutations usually correlate with disease in the thorax, abdomen, or pelvis while SDHD mutations often manifest as head or neck tumors that are typically benign." (PMID 25298897, 2014).
immune diseases (1 paper, 2022). "Abnormalities of SDH activity, which induce immune diseases, are usually associated with metabolic dysfunction, such as the reduced activity of SDHA and SDHB." (PMID 36354983, 2022).
SDHB also shares sentences with these, for which no sentence is quoted: Obesity (4 papers); Adrenal Gland (3); Marfan syndrome (3); osteosarcoma (3); Adrenocortical Cancer (2); Alzheimer disease (2); diabetes (2); glioblastoma (2); hereditary leiomyomatosis and renal cell cancer (2); Huntington disease (2); liver cancer (2); parathyroid adenoma (2); Parkinson disease (2); pituitary tumor (2); tumor predisposition syndrome (2); abortion (1); acromegaly (1); acute lymphoblastic leukemia (1); adenocarcinoma (1); adrenocortical tumors (1); astrocytoma (1); autoimmune gastritis (1); benign neoplasm (1); BHD syndrome (1); brain diseases (1); brain infarction (1); brain tumors (1); cardiac hypertrophy (1); Carney triad (1); cataract (1).
A further 69 diseases each share a sentence with SDHB in 1 paper.